EGFR (epidermal growth factor receptor)
Diseases named in the same sentence as EGFR in open-access papers (continued):
Sharing a sentence is not in itself a finding about the gene and the disease.
bladder cancer (continued). "We next determined whether the concurrent inhibition of autophagy activities by specific suppression of ATG12, one of the key transcription factors for LC3 expression, could also enhance the anti-cancer effects of EGFR inhibitors in human bladder cancer cells." (PMID 28165387, 2017). "In this study, we investigate whether the concurrent treatment of autophagy-blocking agents with EGFR inhibitors exerts synergistic anti-cancer effects in T24 and J82 human bladder cancer cells." (PMID 28165387, 2017). "Considering that autophagy can act as pro-survival machinery under a harsh condition, enhanced autophagy activities by EGFR inhibitor treatment may contribute to drug resistance in bladder cancer." (PMID 28165387, 2017). "More effective and safe autophagy inhibitors should be developed in the future, thus offering a promising therapeutic strategy to overcome resistance to EGFR inhibitors and to improve the anti-cancer effects of these agents for patients with advanced stage bladder cancer." (PMID 28165387, 2017). "Here, we investigate to determine whether the concurrent autophagy inhibition can overcome the drug resistance of EGFR inhibitors in human bladder cancer cells in vitro." (PMID 28165387, 2017). "Also, research is being conducted with erlotinib, highly selective, reversible inhibitor of epidermal growth factor receptor (HER1/EGFR) tyrosine kinase which is overexpressed in more than 75% of bladder cancers." (PMID 28423681, 2017). "Considering that EGFR inhibitors activate autophagy in bladder cancer cells, we proceeded to determine whether concurrent inhibition of autophagy activities can enhance the anti-cancer effects of EGFR inhibitors." (PMID 28165387, 2017). "Curcumin decreased expression of EGFR, and also EGFR mRNA levels in bladder cancer cells." (PMID 27834913, 2016). "Additionally, the expression of Ki67 and EGFR were important in predicting primary superficial bladder cancer recurrence and secondary bladder cancer after RNU." (PMID 27870887, 2016). "Most bladder cancers express elevated levels of the epidermal growth factor receptor (EGFR)." (PMID 26930657, 2016). "Thus, biological pathways that enhance growth factor signaling through EGFR are likely to contribute to bladder cancer progression and metastasis." (PMID 26930657, 2016). "The communication between the AR and EGFR pathways may play a role in the male prevalence in bladder cancer." (PMID 26347776, 2015). "A next step is to determine whether altered levels of EGFR and USP2a are correlated with more aggressive bladder cancer, and whether these combined two molecular markers might predict aggressive disease." (PMID 26250800, 2015). "Moreover, EMT regulators have been shown to modulate resistance to EGFR inhibitors in bladder cancer." (PMID 25171249, 2014). "Although urinary EGFR could serve as a promising prognostic biomarker candidate for bladder cancer, it was identified as a low abundance urinary protein (1 unique peptide and <10 spectrums) and in practice was hard to measure by ELISA (data not shown)." (PMID 24801713, 2014). "Although EGFR-TKi may be ineffective for bladder cancer, some of the major molecular targeting drugs currently available seem to be effective." (PMID 25431734, 2014). "Interestingly, these pathways are downstream of the EGFR and ErbB2 family proteins whose expression and activity are related to bladder cancer progression, as well as ErbB3, FGFR3 and HRAS that are active in superficial tumors." (PMID 23383328, 2013). "Finally, we demonstrated the capacity of upregulation of LRIG1 to inhibit downstream EGFR signaling in bladder cancer cells as manifested by markedly decreased expression of p-MAPK and p-AKT." (PMID 24314030, 2013). "We have shown that high EGFR expression is associated with an aggressive phenotype and that modulation of GSK-3β might be a predictor of response to EGFR inhibitors in bladder cancer." (PMID 23409107, 2013).
bladder cancer (continued). "We do believe that EGFR remains a strong signalling axis in progression of bladder cancer where its inhibition may benefit selected patients." (PMID 23409107, 2013). "Furthermore, we evaluate the impact of LRIG1 gene on the function of human bladder cancer cells and EGFR signaling." (PMID 24314030, 2013). "This has been shown previously in bladder cancer cells where incubation with betulinic acid and curcumin down-regulated specificity protein (Sp) transcription factors and this was accompanied by decreased expression of EGFR mRNA and protein levels." (PMID 22134789, 2012). "We have recently shown that androgens activate the EGFR pathway in bladder cancer cells." (PMID 22922989, 2012). "Consequently, the efficacy of targeted therapy directed at EGFR signals has been assessed in bladder cancer." (PMID 22922989, 2012). "Thus, our results support the possibility that EGF mediates AR transcriptional activity through the EGFR and AR pathways in bladder cancer cells." (PMID 22922989, 2012). "The roles of protein-tyrosine phosphorylation for the anti-apoptosis of cancer cells under serum-starved conditions have recently been fully documented by our studies on bladder carcinoma cell line 5637, whose serum-independent growth involving autocrine ligands for EGFR was reported in the 1990s." (PMID 22988500, 2012). "PIP5K3 has also been proposed as a mediator of EGFR transcription function in bladder carcinoma." (PMID 21284875, 2011). "The assays may also be useful for future therapies targeting the epidermal growth factor receptor (EGFR) in bladder cancer, which are currently tested in clinical trials." (PMID 21072204, 2010). "Epidermal growth factor receptor (EGFR) can be over-expressed in bladder cancer." (PMID 19468365, 2008). "Strategies targeting the EGFR may well have a therapeutic potential in bladder cancer, since the receptor is frequently expressed at high levels in this disease and patients with tumours expressing high levels of EGFR tend to have a poor prognosis." (PMID 15083203, 2004). "Thus, EGFR is an important target for antibody therapies of invasive bladder cancer in humans." (PMID 29721181, 2018). "In addition, EGFR is localized to the basal layer of urothelial cells in normal urothelium, but is extensively present in both the luminal and basal layers in UCC, indicating that an EGFR-target intravesical treatment has potential for use in bladder cancer cell eradication." (PMID 29701711, 2018). "Thus, like Ki-67 and HER-2, EGFR expression could be used as a marker of bladder cancer recurrence after radical therapy." (PMID 29135410, 2018). "Therefore, it is an available choice to target EGFR for the management of bladder cancer." (PMID 27334428, 2016). "To determine whether EGFR expression is critical for the effect of LRIG1 on bladder cancer cells in vitro, we next used specific genetic inhibition of EGFR to assess the consequences of its inhibition on LRIG1 mediated cell proliferation and signal pathway regulation." (PMID 24314030, 2013). "The aim of this study is to investigate crosstalk between these two signalling axes as they share some common downstream signalling effectors and evaluate whether combination of PPARγ agonist and an EGFR inhibitor may overcome resistance to EGFR therapy in bladder cancer." (PMID 23409107, 2013). "Finally, tentative proliferative or anti-proliferative mechanisms can be connected with established bladder cancer deregulations, namely Epidermal Growth Factor Receptor (EGFR) over-expression and Fibroblast Growth Factor Receptor 3 (FGFR3) activating mutations." (PMID 24250280, 2013). "However, crosstalk between AR and EGFR pathways in bladder cancer remains uncharacterized." (PMID 22922989, 2012). "Importantly, previous studies concluded that “mesenchymal” bladder cancer cells are as a group highly invasive and resistant to radiation and EGFR-directed therapy, suggesting they might possess unfavorable biological characteristics." (PMID 22253920, 2012).
bladder cancer (continued). "This study is designed as a 3-arm trial comparing green tea polyphenols with the epidermal growth factor receptor antagonist, erlotinib, and placebo in former smokers with intermediate and high-risk nonmuscle invasive bladder cancer in combination with maintenance bacille Calmette-Guérin (BCG)." (PMID 21941546, 2011). "Likewise, the epidermal growth factor receptor (EGFR) is frequently overexpressed in bladder cancer and might therefore be an important therapeutic target for MI-BC." (PMID 21072204, 2010). "The distribution of the top 5 molecular targets in the global ADC clinical trials in bladder cancer showed that HER2, NECTIN4, immune checkpoints (PD-1), TROP2 and epidermal growth factor receptor (EGFR) were the most widely studied targets." (PMID 40433388, 2025). "A preclinical study has looked at immunoPET to detect EGFR expression in bladder cancer, utilising a radioimmunoconjugate 89Zr-DFO-Panitumumab to specifically target and visualise EGFR in orthotopic bladder tumours." (PMID 39858014, 2025). "EGFR-targeted therapy, cancer immunotherapy, and radiation therapy were effective for patients with high SLC7A5 expression in bladder cancer." (PMID 38790003, 2024). "Phenformin, a derivative of metformin with higher anticancer potency at lower doses, can effectively inhibit bladder cancer growth by activating AMPK signalling and inhibiting EGFR signalling." (PMID 38556542, 2024). "Consistent with this scenario, the findings of a recent study have revealed that by activating the EGFR/ERK/c-Jun pathway, glutamine deprivation can promote the upregulation of PD-L1 in bladder cancer cells." (PMID 36911676, 2023). "Since EGFR and HER2 are predominantly expressed in the basal and luminal subtypes of bladder cancer, respectively, combining both targets provide a unique and highly selective way of targeting bladder cancers that have moderate expression of both." (PMID 36737799, 2023). "Accumulating evidence has also indicated that different kinases, including epidermal growth factor receptor (EGFR), HER2, and/or nuclear factor-κ B, are correlated with the development of cisplatin resistance in bladder cancers." (PMID 38139437, 2023). "Parenthetically, as is to be expected, lapatinib, an EGFR and HER2 inhibitor, was similarly effective when given alone or in combination with an NSAID in our basal bladder cancer model." (PMID 37169023, 2023). "Cisplatin treatment increased EGFR and NF-κB activation and upregulated ProT and HOTAIR expression in bladder cancer cells." (PMID 36471329, 2022). "Studies showed that bladder cancer cells promoted tumor progression interacting with vascular endothelial cells through the VEGFR2 and EGFR signaling pathway." (PMID 35422849, 2022). "A further two (EGFR and HDAC3) are known to be highly expressed in bladder cancer and are also being targeted by drugs for bladder cancer." (PMID 35035776, 2022). "The bladder cancer category included proteins such as MAPK1 (P28482), EGFR (E9PFD7), SRC (P12931), and ERBB2 (B4DTR1)." (PMID 36362028, 2022). "In summary, our research has identified SHCBP1 as a new mediator of the crosstalk between EGF/EGFR signaling and RAC1 and a new mechanism mediating the progression of bladder cancer." (PMID 35013128, 2022). "A combination of EGFR- and HER2-targeted NIR-PIT had a higher efficacy than either type of NIR-PIT in bladder cancer xenografts alone." (PMID 35740662, 2022). "In bladder cancer, it was noticed that the expression of miR-200 is transcriptionally repressed by XIAP, which in turn upregulates the level of EGFR, a target of miR-200." (PMID 33435156, 2021). "The KEGG pathway analysis showed that the identified DEGs were mainly enriched in the following top five pathways: proteoglycans in cancer, bladder cancer, malaria, tyrosine kinase inhibitor resistance in EGFR, and the ERBB signaling pathway." (PMID 33828969, 2021).
bladder cancer (continued). "This study, carried out in kidney and bladder cancer cell lines, established the paradigm in which LPA (and other GPCR agonists) can induce the release of EGFR ligands that activate EGFR in an autocrine manner." (PMID 34440828, 2021). "In bladder cancer, ALDOA was reported to act as an oncogene by interacting with E-cadherin-epidermal growth factor receptor (EGFR) signaling, leading to cancer cell metastasis." (PMID 34458323, 2021). "High expression levels of FOXO3, EGFR, and GPC1 as well as low expressions of VEGFA were closely correlated with poorer survival outcomes of bladder cancer patients." (PMID 33962639, 2021). "Next, EGFR and ERBB2/HER2 protein expression was evaluated in a large cohort of bladder cancers with substantial squamous differentiation comprising MIX-SCC (n = 50) and pure SCC (n = 75)." (PMID 32978523, 2020). "These hub nodes such as VEGFA, EGFR, ESR1, PLG, and MAPK3 were mainly enriched in pathways like proteoglycans in cancer, bladder cancer, and estrogen-signaling pathway." (PMID 32256653, 2020). "EGFR and HER2 expression in human bladder cancer were further confirmed using commercially available tissue microarrays of human bladder cancer samples." (PMID 30765854, 2019). "Accordingly, we select the intersection of two gene sets, namely the bladder cancer and PI3K–Akt pathways, which then generates four common genes, EGF, EGFR, THBS1, and VEGFA (EntrezGene ID: 1950, 1956, 7057, 7422)." (PMID 30868054, 2019). "This is not surprising as we have shown that ETV5 expression is modulated by MAPK/ERK signalling, which is a point of convergence of many signalling pathways altered in bladder cancer, such as PI3K, EGFR, and RAS." (PMID 30952872, 2019). "The cell surface EGFR and HER2 expression on various bladder cancer cell lines was determined using flow cytometry." (PMID 30765854, 2019). "This pathway is activated in around 40% bladder cancer cases (FGFR3: > 10%, EGFR:> 10%, ERBB2:~ 10%, ERBB3:~ 10%, NRAS/HRAS/KRAS:~ 10%, PTEN: ~ 10%, AKT3:~ 10%)." (PMID 31665050, 2019). "Four canine urinary bladder cancer cell lines, four mammary gland cancer cell lines, and canine thyroid adenocarcinoma (CTAC) cells were screened for their EGFR and HER-2 expression levels." (PMID 31610784, 2019). "Urinary levels of HAI-1, EpCAM and EGFR were measured by ELISA in 683 and 175 patients with newly-diagnosed NMIBC and MIBC, respectively, recruited to the Bladder Cancer Prognosis Programme." (PMID 29861867, 2018). "Despite these limitations, the present work provides evidence that phenformin can effectively inhibit bladder cancer growth by activating AMPK signaling and inhibiting EGFR signaling." (PMID 30053908, 2018). "Our findings link Derlin-1 with EGFR/ERK/MMP signaling and cancer invasion, which contributes to the understanding regarding mechanism of Derlin-1 in bladder cancer progression." (PMID 28178653, 2017). "More interestingly, EGF and DHT appeared to show synergistic effects on the proliferation as well as phosphorylation of EGFR, AKT, and ERK in bladder cancer cells." (PMID 28241422, 2017). "Five genes in this network (E2F1, E2F3, EGFR, RAF1, and RB1) significantly overlapped genes in the bladder cancer pathway from the Kyoto Encyclopedia of Genes and Genomes (KEGG) database (FDR q<0.01)." (PMID 29140994, 2017). "A total of nine chr3p25 and chr11p11 genes were functionally connected to genes in the KEGG bladder cancer pathway (E2F1, E2F3, EGFR, RAF1, RB1) or to other cancer-related genes (AKT2, PIK3CA, RB1, TRIO)." (PMID 29140994, 2017). "In J82 bladder cancer cells, LC3II expression also increased in a dose- and time-dependent manner after treatment with EGFR inhibitors." (PMID 28165387, 2017). "However, the absence of activating EGFR mutations at exons 19 to 21 in a number of bladder cancer specimens has been demonstrated and may contribute to EGFR inhibitor resistance." (PMID 28775339, 2017).
bladder cancer (continued). "In particular, EGFR and VEGF have been validated as promising molecular targets for the inhibition of bladder cancer growth in preclinical studies." (PMID 27447553, 2016). "In brief, metformin and gefitinib cooperate to inhibit bladder cancer growth via both AMPK and EGFR pathways joining at Akt and Erk and the result were further confirmed through activating EGFR signaling using mEGF." (PMID 27334428, 2016). "Genetic alterations in the mTOR, FGFR, EGFR, and HER2 pathways have long been recognized in subsets of bladder cancer." (PMID 28105319, 2016). "We reported here that in bladder cancer cells, KLF5-VEGFA axis was activated by growth factor EGF and bFGF, PKC agonist PMA and mitogenic lipid LPA, but inhibited by inhibitors of EGFR (AG1478), MEK1/2 (U0126) or PI3K (LY294002)." (PMID 26544730, 2015). "In conclusion, it is of interest to try to target EGFR and/or HER2 for radionuclide based therapy of disseminated urinary bladder cancers to decrease the influence of resistance to other forms of therapy." (PMID 25810701, 2015). "Because PDGFRB/EGFR heterodimers were reported to express on bladder cancer cells, and the EGF/EGFR pathway played an important role in bladder cancer development, PDGFRB was selected for further validation as a candidate biomarker of bladder cancer." (PMID 24801713, 2014). "As evaluated by MTT assays, gefitinib (EGFR inhibitor) and DIM-C (PPARγ agonist) inhibited growth of 9 bladder cancer cell lines in a dose-dependent manner but with variable sensitivity." (PMID 23409107, 2013). "Increased STAT3 phosphorylation has also been observed in EGFR mAb treatment-resistant cell models of head and neck squamous carcinoma (HNSCC) and bladder cancer." (PMID 24280348, 2013). "Overexpression and amplification of epidermal growth factor receptor (EGFR) (HER1 or ErdB1) and, or the HER2 gene is found in bladder cancers." (PMID 23574966, 2013). "Meanwhile, we overexpressed LRIG1 with adenovirus vector in T24/5637 bladder cancer cell lines, and we used real time-PCR, western blot, and co-immunoprecipitation analysis in order to examine the effects of LRIG1 gene on EGFR." (PMID 24314030, 2013). "The aim of this study was to investigate the anti-tumor effects of PDT plus Erbitux, an angiogenesis inhibitor that targets epidermal growth factor receptor (EGFR), on human bladder cancer model." (PMID 19878607, 2009). "Because GM3 has been reported to suppress EGFR phosphorylation in bladder cancer cell lines, it was suggested that further sialylation of GM3 by ST8SIA1 may enhance this inhibitory effect by reducing EGFR, JAK, and STAT3 phosphorylation levels." (PMID 40252176, 2025). "Indeed, EGFR on chromosome 7 and ERBB2 on chromosome 17 have been reported to promote bladder cancer development." (PMID 41139203, 2025). "Gαi3 interacts with receptor tyrosine kinases such as the epidermal growth factor receptor (EGFR) and FGFR, mediating the activation of the downstream PI3K/AKT/mTOR signaling cascade to promote the proliferation, migration, and invasion of bladder cancer cells." (PMID 41438986, 2025). "For example, EGFR, HER2, or CA125 can be selected protein markers of bladder cancer on exosomes." (PMID 39678505, 2024). "Not only EGFR and PDGFRA, but other novel biomarkers are receiving recognition for bladder cancer." (PMID 39678505, 2024).